UCP1 (uncoupling protein 1)
Diseases named in the same sentence as UCP1 in open-access papers (continued):
Sharing a sentence is not in itself a finding about the gene and the disease.
Obesity (continued). "In mice, inhibition of the β3-adrenergic receptor causes obesity, whereas agonists of the receptor elicit anti-obesity effects, such as suppression of food intake and UCP1-mediated thermogenesis." (PMID 24159189, 2014). "Strategies aiming at increasing levels of UCP1 in WAT have become of interest as reduced expression of brown adipocyte-enriched genes in WAT is associated with obesity and type 2 diabetes in humans." (PMID 24059847, 2013). "Given the responses to loss of UCP-1 span the whole range from protection from diet induced obesity at 21°C to susceptibility at 30°C, the question remains which of these responses most closely reflects the situation in humans." (PMID 23504620, 2013). "UCP1 has been reported to play an important role in thermogenesis and energy expenditure and is implicated in the pathogenesis of obesity and metabolic disorders in human." (PMID 23134754, 2012). "The FTO SNP rs9939609 and UCP-1 SNP rs6536991 demonstrated a statistically significant association with the obesity phenotype as measured by BMI (p= 0.04 and p< 0.0001 respectively)." (PMID 23134754, 2012). "Uncoupling protein-1 (UCP-1), which plays a major role in thermogenesis and energy expenditure can increase the risk of obesity and can be related metabolic disorders." (PMID 23043591, 2012). "Our data are consistent with FTO rs9939609 and UCP-1 rs6536991 common variants as contributors to obesity in the Brazilian population." (PMID 23134754, 2012). "UCP1 plays important roles in energy homeostasis, and UCP1 gene polymorphisms have been implicated in the pathogenesis of obesity and related metabolic disorders, including lipid disorders." (PMID 22393344, 2011). "The UCP-1 expression is regulated by the extent of obesity, and the G allele has been reported to be related to a reduction of the expression of the gene in an obese population." (PMID 22393344, 2011). "Polymorphisms of UCP1 have been associated with fat metabolism, obesity, and diabetes, which are known to have different distributions in men and women." (PMID 22087257, 2011). "The UCP-1 expression is regulated by the condition of the individual, including the extent of obesity, and carrying the G allele is related to a reduced UCP-1 expression in obese subjects." (PMID 22393344, 2011). "The unique energy-dissipating ability of UCP1 makes control of its expression and activation potential targets for the development of novel drugs for the treatment of obesity and obesity-associated diseases." (PMID 20613988, 2010). "In mice, an increased content of UCP1 in adipose tissue mitochondria is strongly linked to protection against diet-induced obesity." (PMID 20613988, 2010). "Human obesity is associated with a reduced expression of UCP1 and other thermogenesis related genes in WAT depots." (PMID 20613988, 2010). "Ate1-deficient mice are also resistant to diet-induced obesity and exhibit ectopic induction of the Ucp1 uncoupling protein in white adipose tissue (WAT)." (PMID 19915679, 2009). "Associations with obesity, weight gain and metabolism have been reported for UCP1 variant A3826G, often acting synergistically with β3-adrenergic receptor W64R, and UCP1 A64T has also been associated with obesity." (PMID 17397545, 2007). "In fact,obesity models in rodents are in most cases associated with lowlevels and activity of UCP1 in brown fat." (PMID 17389766, 2007). "Specifically, the RNA-binding protein QKI plays an important role in restricting energy consumption of adipose tissue by regulating UCP1 and PGC1α, thereby promoting high-fat diet-induced obesity, while QKI deficiency enhances brown fat thermogenesis and white fat browning." (PMID 41199171, 2025). "Increase of UCP1 in the WAT of Clcn3 knockout mice, suggesting that UCP1 may be a target for Clcn3 deficiency to prevent obesity." (PMID 38784133, 2024).
Obesity (continued). "Obesity was associated with a significant reduction in the gene expression of Fasn (p < 0.05), Lpl (p < 0.01), Hsl (p < 0.001), Ppar-γ (p < 0.001), Pgc-1α (p < 0.001), Ucp-1 (p < 0.05), β3-Adr (p < 0.001) and Ob-r (p < 0.05)." (PMID 37239868, 2023). "At the protein level, we observed that active beige adipocytes expressed more UCP1 as compared to white or inactive beige adipocytes regardless the FTO rs1421085 genotypes, however, less UCP1 protein amount was detected in obesity-risk than in risk-free allele carrier active beige adipocytes." (PMID 37416800, 2023). "Obesity is associated with lower VAT UCP-1, -2 and -3 expression." (PMID 36675195, 2023). "Therefore, numerous genetic studies investigated the association between UCP1 gene single nucleotide variations (SNVs) and the risk of obesity, T2DM, and MetS." (PMID 37107547, 2023). "Obesity reduces the thermogenic potential of the adipose tissue, polymorphic UCP1 increases the risk of liver disease in obese patients, and the premature loss of thermogenic potential is thought to favor storage fat development and potentially lead to childhood obesity." (PMID 38069028, 2023). "Active beige adipocytes with FTO obesity-risk variant showed lower cellular respiration, especially stimulated proton leak respiration which reflects UCP1-dependent heat production, and extracellular acidification, which associates with glycolytic activity, as compared to risk-free carriers." (PMID 37416800, 2023). "Similarly, adult obesity has been shown to be associated with a reduced UCP1 expression in the subcutaneous adipose tissue." (PMID 38069028, 2023). "It prevents obesity caused by diet and hypothermia, through uncoupling protein 1 (UCP1)." (PMID 37629668, 2023). "Conversely, an overexpression of UCP1 is associated with an anti-obesity effect." (PMID 37107352, 2023). "However, in reality, there is a deficit of studies demonstrating the validity of what seems to be the underlying tenet: that augmented UCP1 amounts in themselves protect against obesity." (PMID 37499977, 2023). "These obesity-associated factors likely affect mitochondrial energy status and UCP1-mediated thermogenesis; however, the relationship remains unclear." (PMID 36674862, 2023). "In addition, the structure of the human protein UCP1 has recently been obtained, which can help in the development of drugs for obesity and various complications associated with metabolism." (PMID 37762355, 2023). "The issue under discussion here is whether a decrease in the degree of UCP1 activity (and brown adipose tissue activity in general) could be a cause of obesity in humans." (PMID 37661736, 2023). "The promotional effect of TRPV1 and UCP1 depletion on obesity and hypertension is associated with impaired energy expenditure and spontaneous activity, which might be a reflection of lower mitochondrial function." (PMID 35043013, 2022). "Furthermore, ectopic expression of UCP1 in scWAT from KY19334-treated mice was linked to protecting against diet-induced obesity by increasing fatty acid oxidation of scWAT." (PMID 36114279, 2022). "Furthermore, ectopic expression of UCP1 in scWAT from KY19334-treated mice was linked to protecting diet-induced obesity by increased fatty acid oxidation of scWAT." (PMID 36450849, 2022). "Therefore, we examined the effects of DIO2 Thr92Ala (rs225014), UCP1-3826 A/G (rs1800592), and β3AR Trp64Arg (rs4994) polymorphisms on obesity in Japanese children." (PMID 36291357, 2022). "Therefore, the regulatory effect of Fx in UCP1-mediated thermogenesis underlies its anti-obesity effect." (PMID 35736173, 2022). "Additionally, studies have also demonstrated that BAs reduce obesity susceptibility by increasing the expression and activity of uncoupling protein 1 (UCP1) and increasing energy expenditure by GLP-1." (PMID 36219347, 2022).
Obesity (continued). "A high level of Irisin in mice has also been found to increase the expression of uncoupling protein 1 (UCP1) in adipocytes, promote the conversion of white fat to brown fat, increase energy expenditure, reduce obesity caused by a high-fat diet, and enhance glucose tolerance." (PMID 36111165, 2022). "These controls of UCP1 activity represent potential targets of therapeutic interventions to unlock constraints and efficiently harness the energy-expending potential of brown fat to prevent and treat obesity and associated metabolic disorders." (PMID 35269549, 2022). "Decreased Ucp1 expression is associated with obesity and type 2 diabetes." (PMID 34527816, 2021). "In addition to the effect of fucoxanthin on lipase activity, several studies have shown that the anti-obesity effect of fucoxanthin is associated with fatty-acid oxidation and heat production by inducing uncoupling protein 1 (UCP-1) in white adipose tissue." (PMID 33567531, 2021). "Further, increasing the expression of Ucp-1 may induce weight loss and be employed to treat obesity." (PMID 33668504, 2021). "It was previously demonstrated that a high-fat diet with n-3 PUFA could increase energy expenditure in UCP1-deficient mice and be protective against obesity by increasing energy dissipation." (PMID 34940596, 2021). "However, early studies in Ucp1 knockout mice were incapable of establish a clear connection between UCP1 deficiency and obesity." (PMID 34829617, 2021). "UCP1-deficient mice maintained in a room at 23 °C developed obesity with age; therefore, UCP1 may play an important role against obesity." (PMID 34067796, 2021). "For example, the adrenergic receptor beta-2 (ADRB2), adrenergic receptor beta-3 (ADRB3), guanine nucleotide-binding protein (GNB3), uncoupling protein 1 (UCP1), and fat mass- and obesity-associated (FTO) genes are all reported to have associations with obesity." (PMID 34055005, 2021). "UCP1 plays a vital role in metabolic and energy balance and regulation, cold- and diet-induced thermogenesis, and decreasing the production of reactive oxygen species by mitochondria, which are mechanisms associated with the pathogenesis of obesity." (PMID 34055005, 2021). "Our findings indicate that GD administration upregulates UCP1, which may be associated with an active browning process that finally results in anti-obesity effects." (PMID 34646848, 2021). "In this therapeutic context, it is important to mention that mutations in the UCP1 gene could be involved in the pathology of obesity." (PMID 32069871, 2020). "Correspondingly, the anti-obesity impact of FXN may be linked to the browning of white adipocytes through the upregulation of UCP1, which yields increments in energy expenditure in the body." (PMID 32260306, 2020). "Using two distinct mouse models we subsequently demonstrate that genetic deletion of Tph1 in mast cells reduces WAT serotonin and enhances WAT Ucp1 and whole-body energy expenditure; an effect associated with a reduction in high-fat diet-induced obesity, insulin resistance and NAFLD." (PMID 31974364, 2020). "In addition, UCP1 ablation resulted in increased obesity and metabolic deficiency in obesity-resistance mouse strain." (PMID 32717874, 2020). "Moreover, MRTF-A deficient mice exhibit reduced obesity, improved glucose tolerance, and increased beige fat and UCP-1 expression, a phenotype similar to our DDR1-deficient mice." (PMID 32360427, 2020). "Indeed, C57BL7 mice deficient for IL-18 are extremely sensitive to obesity but also exhibit larger brown adipocytes and a higher UCP-1 expression in BAT compared to wild-type littermates." (PMID 31366145, 2019). "H. polygyrus-mediated reduction in obesity is associated with UCP1 expression induced via NE." (PMID 30962398, 2019).
Obesity (continued). "To examine whether the protection against diet-induced obesity observed above in WT versus UCP1-KO mice would be associated with a recruited UCP1-dependent thermogenic capacity, we determined adrenergically-induced O2 consumption." (PMID 30807213, 2019). "The associated UCP1 polymorphisms in the moderate-obese group may regulate impaired energy metabolism which plays a significant role in the initial stages of obesity." (PMID 30458724, 2018). "The associated UCP1 polymorphisms in the moderate-obese group may regulate the impaired energy metabolism which plays a significant role in the initial stages of obesity." (PMID 30458724, 2018). "We selected the most studied polymorphisms of the UCP1 gene with respect to obesity." (PMID 30458724, 2018). "Concerning anti-obesogenic pollutants„ we discussed the effect of perfluorooctane sulfonate (PFOS) and perfluorooctanoic acid (PFOA), which have a reverse association with obesity and are associated with UCP1 upregulation and increased oxidative capacity in brown-fat mitochondria." (PMID 30687113, 2018). "Obesity has also been shown to inhibit metabolic responses of BAT to ephedrine, insulin, or cold exposure; however, it is still unknown whether HFD-induced Ucp1 downregulation is related to causation, or whether it is a consequence of obesity." (PMID 29473916, 2018). "Concluding from the observed association of IRX3 expression with FTO obesity risk variants and UCP1 expression in adipocytes of lean children, one may expect increased IRX3 expression in obese subjects." (PMID 27560134, 2016). "Notably, irisin replenishment in mCaROCK1 mice partially reversed insulin resistance and obesity and these changes were associated with increased expression of UCP1 and Pref-1 in subcutaneous WAT." (PMID 27411515, 2016). "Thus, the loss of BAT mass, such as the severe brown lipoatrophy induced by the insulin receptor deletion in that tissue, or the loss of UCP-1 confers susceptibility to obesity in mice." (PMID 27766104, 2016). "Much emphasis has been placed on manipulating UCP1 in order to increase thermogenesis and thus energy expenditure, which over time would reduce adiposity and consequently correct metabolic abnormalities associated with obesity." (PMID 26528238, 2015). "In addition, it has been shown that genetic variants of UCP1 are associated with fat metabolism, obesity, and diabetes." (PMID 25713540, 2015). "UCP1-deficient mice are cold-sensitive, and when housed at thermoneutrality (i.e., in the absence of cold-induced thermogenesis), they exhibit an increased susceptibility to diet-induced obesity." (PMID 25658324, 2015). "The aims of this review are to describe some of the main factors regulating UCP1 activity in brown and brite adipocytes, as well as to discuss the potential role of UCP1 activation for the treatment of insulin resistance and type 2 diabetes associated with obesity." (PMID 25688211, 2015). "Furthermore, no data concerning the relationships between the β3-AR Trp64Arg and UCP1 -3826A > G polymorphisms and overweight/obesity and lipid profiles have been reported for a Southwest Chinese population." (PMID 25928572, 2015). "UCP-1 expression in BAT is closely linked to obesity and diabetes." (PMID 25144367, 2014). "In addition, many association studies were also performed in various populations to elucidate the potential contribution of UCP1 polymorphisms to various obesity phenotypes." (PMID 23134754, 2012). "A-3826G and A-1766G UCP-1 polymorphisms, which are related to obesity, might be candidate genetic markers for DP pattern in the TKM diagnosis system." (PMID 23043591, 2012). "We assessed the requirement of p300 or CBP in thermogenic fat using uncoupling protein 1 (Ucp1)-Cre-mediated knockdown in mice to determine whether their loss impacted tissue development, susceptibility to diet-induced obesity, and response to pharmacological induction via β3-agonism." (PMID 39140972, 2024).
Obesity (continued). "The most common polymorphisms studied in relation to MetS, T2DM, obesity, BMI, and lipid disorders were: –3826A/G (rs1800592), –112A/C (rs10011540), and –1766A/G (rs3811791) in the 5′-region, Ala64Thr (rs45539933) in exon 2, and Met229Leu (rs2270565) in exon 5 of the UCP1 gene." (PMID 37107547, 2023). "We propose that these brakes on UCP1 activity represent potential targets of therapeutic interventions to unlock constraints and efficiently and fully harness the energy-converting potential of brown fat to prevent and treat obesity and associated metabolic disorders." (PMID 35269549, 2022). "Since UCP1 G/G genotype is a well-studied gene linked to the onset of obesity and insulin resistance, it is possible to cater specific treatment based on what is needed via SNP analysis as this G/G allele individuals might be at higher risk of developing the obesity-related disorder." (PMID 35954003, 2022). "Furthermore, SNPs in the UCP1 gene have been associated with obesity." (PMID 36532520, 2022). "Therefore, the regulatory mechanism underlying UCP1 expression may assist in identifying anti-obesity drugs as well as dietary compounds targeting human brown adipocytes." (PMID 35805122, 2022). "Thus, in both humans and rodents, the association between obesity and UCP1 expression is inverse." (PMID 33924341, 2021). "In a Korean study on the relationship between gene polymorphisms and Phlegm syndrome, A-3826G and A-1766G polymorphisms in the UCP-1 gene known as obesity-related polymorphisms could be used as candidate genetic markers for the Phlegm-Dampness syndrome in stroke patients." (PMID 33671865, 2021). "The anti-obesity mechanism of fucoxanthin has been linked to the upregulation of uncoupling protein 1 (UCP1), which is a key molecule for metabolic thermogenesis to avoid an excess of fat accumulation, and acts as a physiological defense against the onset of obesity." (PMID 32260306, 2020). "Increased peripheral 5-HT is associated with obesity, while inhibition of peripheral 5-HT synthesis reduces metabolic dysfunction related to obesity by promoting thermogenic activity in brown adipose tissue via activation of uncoupling protein 1 (UCP1)-mediated thermogenesis." (PMID 32825115, 2020). "Moreover, genetic variants of UCP1 are associated with fat metabolism, obesity, and diabetes." (PMID 30687113, 2018). "Several studies have reported that polymorphisms of the UCP1 gene such as, g.-3826A > G (rs1800592), g.-1766A > G (rs10011540) and g.-112A > C (rs3811791) in the promoter region, and p.Ala64Thr (rs45539933) and p.Met299Leu (rs2270565) in the codon region are associated with obesity and T2DM." (PMID 30458724, 2018). "A significant association of UCP1 polymorphisms rs3811791 was observed only in the moderate-obese cohort [OR = 2.89 (1.33–6.25); p = 0.007] but not in the extreme-obese cohort indicating an overlying genetic complexity between moderate-obesity and extreme-obesity." (PMID 30458724, 2018). "However, at 30°C, the Ucp1-KO mice are more susceptible to obesity than their wild type littermates and become by far more obese, demonstrating the importance of UCP1 for diet-induced thermogenesis and prevention of obesity development." (PMID 30631281, 2018). "In addition, an elevation of UCP1 expression was confirmed in white adipose tissues from Pdcd4-deficient mice upon high-fat diet, which displayed increased energy expenditure and resistance to obesity as compared with wild-type obese mice." (PMID 27031966, 2016). "Therefore, we undertook this population-based study to assess whether the β3-AR Trp64Arg and UCP1 -3826 A > G polymorphisms were related to overweight/obesity and lipid profiles in a Southwest Chinese population." (PMID 25928572, 2015).